IL1B (interleukin 1 beta)
Diseases named in the same sentence as IL1B in open-access papers (continued):
Sharing a sentence is not in itself a finding about the gene and the disease.
abortion (5 papers, 2013 to 2025). the ending of pregnancy by removing a fetus or embryo before it can survive outside the uterus. "A higher M1/M2 ratio of dMφs was demonstrated in spontaneous abortion, which manifested a higher expression of M1-associated markers (CD86, CD80, and IL-1β) and lower expression of M2-associated markers (CD209, CD206, IL-10, and TGF-β1." (PMID 37033974, 2023). "The results showed that the mean plasma level of IL-1β, IL-6 and TNF-α in repeated abortion were markedly higher than those in control group." (PMID 30061639, 2018). "Experimentally infected mares expressed more IL-6, IL-8, IL-1β, and TNF-α mRNA in the cervical star region and produced high concentrations of PGE2 and PGF2α in allantoic fluid, leading to abortion or birth of a precociously mature foal." (PMID 23390521, 2013). "Moreover, in the CBA/J × DBA2 spontaneous abortion mouse model, increasing pregnant mice succinate levels via intraperitoneal DMS injection resulted in increased IL-1β levels in mouse villi samples, and significantly decreased the embryo-resorption rate." (PMID 34103526, 2021).
aging (5 papers, 2016 to 2025). A developmental process that is a deterioration and loss of function over time. "The key cytokines involved in the pathogenesis of skin aging included interleukins such as IL-6, COL-I, TNF-α, and IL-1β." (PMID 40872627, 2025).
anthrax (5 papers, 2010 to 2015). "Mice resistant to Bacillus anthracis have macrophages expressing Nlrp1b variants which confer macrophage sensitivity to anthrax LT, and resistance is linked to the IL-1β response induced by toxin." (PMID 24626226, 2014). "Comparison of circulating neutrophil levels and IL-1β responses in Nlrp1bS/S,Nlrp1bR/R and IL-1 receptor knockout mice implicated Nlrp1b and IL-1 signaling in control of neutrophil responses to anthrax infection." (PMID 21170303, 2010). "Both strains showed similar susceptibility to B. anthracis, indicating that Nlrp1b-mediated protection from anthrax requires IL-1β signaling." (PMID 22241984, 2011). "During anthrax infection, B. anthracis has been known to reach 107-108 organisms per milliliter of blood and induce high amount of cytokines such as TNF-α, IL-6, and IL-1β in primary macrophages and an experimental animal model." (PMID 25472474, 2014). "Elevated transcription of TNF-α, IL-1α, IL-1β, IL-4, IL-6, CCL5, CXCL2 and KC have been observed in both murine anthrax challenge models and in vitro macrophages and monocytic cell lines exposed to anthrax antigens." (PMID 26075052, 2015). "In total, these data indicate that IL-1β plays different roles, i.e., for the ERP it is sufficient but not necessary, but for resistance to anthrax it is necessary." (PMID 22241984, 2011).
asbestosis (5 papers, 2012 to 2021). A lung disorder caused by inhalation of asbestos fibers. "We treated with anti-interleukin 1 beta targeted antibody canakinumab a 67 year old man with asbestosis and long lasting systemic autoimmune features." (PMID 26071911, 2015).
aseptic meningitis (5 papers, 2013 to 2023). Inflammation of the membranes surrounding the brain and spinal cord without a bacterial pathogen. "Moreover, only one MEFV mutation was found in a subset of FMF patients, although FMF is traditionally considered an autosomal recessive disease, and both NLRP3-related diseases and FMF are IL-1β activation disorders, which may cause aseptic meningitis." (PMID 23432807, 2013). "Strong arguments in support of this is a study of patients with aseptic meningitis revealing CSF IL-1Ra levels approximately 2,000 times the level of IL-1β." (PMID 31101054, 2019). "Another meta‐analysis showed elevated levels of IL‐1β in CSF in aseptic meningitis patients." (PMID 37904697, 2023).
astroglioma (5 papers, 2012 to 2025). "A growing body of evidence highlights the regulatory role of microRNAs (miRNAs) in modulating TNF-α and IL-1β signaling in astrocytic tumors." (PMID 40565357, 2025). "The potential effect of a chronic exposure to levetiracetam on IL-1β and Kir4.1 protein expression was further investigated in surgical astrocytic tumor specimens from patients treated with levetiracetam." (PMID 23270518, 2012). "IL-1β has been reported to up-regulate CXCR4 expression in astroglioma cells." (PMID 26176534, 2015). "To investigate potential epigenetic regulation of inflammatory mediators, we analyzed the promoter methylation status of TNF-α, IL-1β, MAP3K8, and MAP2K7 in astrocytic tumors across different malignancy grades." (PMID 40565357, 2025). "In astroglioma cells, OSM induces an approximately three-fold increase in VEGF, while OSM and IL-1β together induce an approximately seven-fold increase of VEGF after 48 hours in astroglioma cells, in a STAT3 dependent manner." (PMID 37841259, 2023).
autoimmune inner ear disease (5 papers, 2015 to 2022). A syndrome characterized by rapidly progressive sensorineural hearing loss (SNHL), that is often bilateral, and is potentially reversible. "Our previous studies have demonstrated elevated interleukin-1β (IL-1β) levels in corticosteroid-unresponsive autoimmune inner ear disease (AIED) patients." (PMID 35322136, 2022). "Gevokizumab, an antibody targeting pro-inflammatory cytokine IL1β is under clinical evaluation, for treatment of autoimmune inner ear disease." (PMID 25688206, 2015).
behavioral disorders (5 papers, 2018 to 2024). "These behavioral disorders caused oxidative stress damage in the hippocampus and changes in NLRP3, IL‐1β and BDNF levels." (PMID 39443283, 2024). "In APP/PS1 transgenic mice, EGCG is reported to improve behavioral disorders, inhibit microglia activation, decrease IL-1β secretion and increase the release of IL-10 and IL-13 in the hippocampus." (PMID 36353622, 2022). "Findings showed that the number of tonic-clonic seizures, atrophy, and cell death in the hippocampus and cerebellum, the gene expression of TNF-α and IL-1β in the hippocampus, and behavioral disorders were significantly increased in the hypoxia rats compared to the sham group." (PMID 39483191, 2024). "In vivo studies, quercetin is reported to improve aging-, or LPS-induced behavior disorders, inhibit microglia and astrocytes activation, as well as decrease IL-1β levels via elevating SIRT1 protein expression and suppressing NLRP3, cleaved-Caspase-1 protein production in the brain of mice." (PMID 36353622, 2022).
bone metastasis (5 papers, 2016 to 2023). Transfer of a neoplasm from its primary site to bones. "Especially, a significant correlation between the expression of IL1β and bone metastasis has been reported: 37% of patients with IL1β-positive primary tumours developed bone metastasis compared with 5% of patients with IL1β-negative primary tumours." (PMID 36230739, 2022). "Previous studies have found that the increase in IL-1β is be involved in bone metastasis." (PMID 35626430, 2022). "Our new data indicate that IL-1B is increased in both the primary and metastatic site prior to the onset of metastasis and blocking activity of the IL1R inhibits development of bone metastasis." (PMID 31783893, 2019).
Brain atrophy (5 papers, 2017 to 2026). Partial or complete wasting (loss) of brain tissue that was once present. "In human MCI and AD retinas, we further delineate a Chlamydia pneumoniae–linked NLRP3 inflammasome axis that converges on IL1β processing, apoptosis, and pyroptosis, and retinal and brain atrophy." (PMID 41571675, 2026). "The CSF of patients with MS contains abundant granzyme B and IL-1β, and CSF IL-1β concentrations correlate with MS-associated brain atrophy." (PMID 28655310, 2017). "In vivo, hampered TRPV1 function significantly reduced brain atrophy, infarct size, and the number of IL-1β-positive astrocytes in the hippocampus." (PMID 31142341, 2019). "Though there is a published correlation between IL-1β in CSF and brain atrophy, no published studies have correlated granzyme B levels with clinical or radiographic measures of pathology in progressive forms of MS." (PMID 28655310, 2017). "In addition, the brain atrophy and infarct size of TRPV1 KO mice after HI were decreased, which was found to be closely related to suppressing the activation of astrocytes and releasing astrocyte-derived IL-1β, mainly via JAK2-STAT3 signaling and activation of the NLRP3 inflammasome." (PMID 34691200, 2021).
calcification (5 papers, 2016 to 2022). Process by which organic tissue becomes hardened by the physiologic deposit of calcium salts. "Anti-IL-1β therapy might reduce the incidence of cardiovascular events by affecting atherosclerotic vascular calcification, but the mechanism underlying this effect remains unclear." (PMID 34803503, 2021). "This study outlines a pathophysiological signaling mechanism to understand the rationale of the action of IL-1β in the development of atherosclerotic vascular calcification." (PMID 34803503, 2021). "Human calcifications were able to induce a significant release of IL-1β when incubated with monocytes, macrophages, and THP-1 only if they were first primed with LPS (monocytes and macrophages) or PMA (THP-1)." (PMID 33926523, 2021). "These future studies will provide us with a broad understanding of IL-1β roles in atherosclerotic vascular calcification, and will define the value of IL-1β as a potential therapeutic target in the treatment of patients with cardiovascular diseases." (PMID 34803503, 2021). "Recent studies, including those summarized in this review, have shown that IL-1β plays prominent roles in the development of atherosclerotic vascular calcification." (PMID 34803503, 2021). "Future research should aim to delineate these molecular mechanisms, including those involving IL-1β-mediated pathways, as related to the development of atherosclerotic vascular calcification." (PMID 34803503, 2021). "Therefore, further clinical trials, especially RCT studies, are needed to explore the roles of IL-1β and related therapeutics in atherosclerotic vascular calcification." (PMID 34803503, 2021).
chronic endometritis (5 papers, 2016 to 2023). A non-granulomatous or granulomatous chronic inflammation of the endometrium. "Furthermore, a logistic regression analysis provided evidence that the IL-6/TNF-α-based model, excluding IL-1β, is a significant predictor of chronic endometritis, which is in accordance with the present results." (PMID 27152525, 2016). "The statistical analysis showed significant correlations between chronic endometritis and the levels of TNF-α, IL-1β, and LIF cytokines (p < 0.0001), and also between chronic endometritis and hysteroscopic findings (p < 0.0001)." (PMID 37835791, 2023). "Nonetheless, in another study, IL-6, IL-1β and TNF-α levels were investigated in menstrual effluents of women with chronic endometritis." (PMID 27152525, 2016). "For this aim, expression of mRNAs for Toll-like Receptor 2 and 4 (TLR 2/4), interleukin 1β (IL-1β), interleukin 6 (IL-6) and tumor necrosis factor α (TNF) was examined in control mares versus either mares suffering from chronic endometritis (ChE) or subacute suppurative endometritis (SSE)." (PMID 27152525, 2016). "As regards the uterine cytokines, we found higher levels of IL-1β and TNF-α, and lower levels of LIF in patients with chronic endometritis, regardless of the KIR genotype." (PMID 37835791, 2023).
cocaine addiction (5 papers, 2015 to 2023). "Previous studies have identified the microglia-derived pro-inflammatory factor IL1β can promote the progression of cocaine addiction." (PMID 34683104, 2021). "The plasma concentrations of interleukin 1-beta (IL-1β), IL-6, IL-10, and tumor necrosis factor-alpha (TNFα) were affected by history of cocaine addiction and sex." (PMID 25762940, 2015). "The IL-1β concentrations were significantly affected by history of cocaine addiction (F1,122 = 5.73, p = 0.018) and by sex (F1,122 = 20.41, p < 0.001)." (PMID 25762940, 2015). "Similarly, inhibition of IL‐1β in the ventral tegmental area prevents cocaine‐induced dopamine release in the nucleus accumbens whereas neuronal NFκB is essential for amplification of cocaine addiction, further implicating neuroimmune signaling in addictive behaviors." (PMID 34415075, 2021). "On one hand, elucidating the mechanistic role of TLR4, IL-1β and TNF-α in cocaine-induced behavior is essential to ameliorate the understanding of progression and maintenance of cocaine addiction." (PMID 34349653, 2021). "Upstream non-key genes (FGF2, VEGFA, and IL1B) affect the expression of downstream genes in this pathway, while MAP2K2 regulates ERK through phosphorylation, thereby affecting cocaine addiction." (PMID 37469839, 2023).
complication (5 papers, 2014 to 2025). Any disease or disorder that occurs during the course of, or because of, another disease, treatment, or procedure. "The observed induction of IL-6, IL-1β and TNFα in hypercoagulable diabetic mice is consistent with these observations and with the perception of diabetic vascular complications as inflammation-driven diseases." (PMID 35631132, 2022). "Patients presenting with pulmonary complications exhibited significantly higher concentrations of IL-1β, IL-6, IL-12, and IFN-γ compared with those who presented without pulmonary complications." (PMID 24696530, 2014).
demyelination (5 papers, 2016 to 2025). "Antioxidant, shown to reduce interleukin-1 beta and tumor necrosis factor alpha in preclinical demyelination models." (PMID 30405407, 2018). "In the current study, we confirmed that inhibition of TRPV4 activity with RN-1734 suppressed microglial and astrocytic activation and decreased the production of IL-1β and TNF-α in mice with CPZ-induced demyelination." (PMID 30455633, 2018). "Similarly, we found caspase-1, GSDMD, NLRP3 and IL-1β mainly localize in microglia, suggesting microglia as the dominating cell type that undergo pyroptosis in our LPC-induced demyelination model." (PMID 36803990, 2023). "Brain tissue from control animals and from animals that did not develop clinical EAE did not contain detectable demyelination, inflammatory activity, or IL-1β." (PMID 27266875, 2016).
diarrhoea (5 papers, 2008 to 2024). "This change can lead to microbiota changes, increased intestinal permeability, and decreased absorptive function accompanying the overproduction of inflammatory cytokines such as IL-6, TNF-α, and IL-1β with ageing, thereby causing diarrhoea." (PMID 34946386, 2021). "Hence the effects of IL-1β could play a major role in the development of diarrhoea." (PMID 18700003, 2008). "In addition, quercetin also significantly reduced diarrheal stools, the expression of IL-1β and TNF-α, and increased the NO level in an EPEC-induced diarrhea rat model." (PMID 39246650, 2024).
endometrial tumor (5 papers, 2019 to 2025). "IL-1β was also found to be highly produced in endometrial tumors." (PMID 31105699, 2019). "Therefore, the elevated production of IL-6 and IL-1β in the endometrial tumors might participate to local inflammation as well as cytotoxic effector inhibition and disease progression." (PMID 31105699, 2019). "All together, we showed that both cytokine and chemokine production in the endometrial tumors may participate to the alteration of NK cell function, as IL-6 and IL-1β are increased in the tumor, and recruitment, as chemoattractants CCL27, CXCL12, and CCL21 are significantly reduced in the tumor." (PMID 31105699, 2019).
Focal cortical dysplasia (5 papers, 2017 to 2024). A type of malformation of cortical development that primarily affects areas of neocortex. "Perhaps the elevation of inflammatory factors is related to the underlying disease itself, as previous literature has suggested that inflammatory factors such as IL-1β and HMGB1 are overexpressed in conditions like focal cortical dysplasia, medial temporal sclerosis." (PMID 39184857, 2024). "Increased levels of IL-1β, and IL-1β Ra, and the β-amyloid precursor were also described in specimens of patients with refractory temporal lobe epilepsy (TLE), who underwent surgery for glioneural tumors or focal cortical dysplasia." (PMID 31156384, 2019).
functional dyspepsia (5 papers, 2016 to 2025). "In functional dyspepsia (FD) model rats, auricular vagus nerve stimulation downregulates serum interleukin-1β (IL-1β) levels, reduces visceral hypersensitivity, and alleviates dyspeptic symptoms." (PMID 40171499, 2025). "In the present study, it is shown that BHM may play a critical role in treating functional dyspepsia via regulating IL1B, TNF, TRPV1, SERT, and NOS3 signaling pathways." (PMID 35668782, 2022). "In H. pylori negative functional dyspepsia patients, plasma cytokines IL-1β, IL-10, and TNF-α levels are increased compared to healthy subjects." (PMID 35527812, 2022). "The increased IL1B, TNFT, RPV1, and NOS3 expression in the duodenum of functional dyspepsia model mice were significantly affected following BHM treatment, suggesting that BHM regulates duodenum functionality and reduces inflammatory response by targeting these genes." (PMID 35668782, 2022). "In H. pylori negative functional dyspepsia patients, peripheral blood mononuclear cell mediated release of cytokines IL-1β, IL-10, IL-6, and TNF-α were correlated with intensity of pain and cramps, and also nausea, vomiting and delayed gastric emptying, which can lead to reduced food intake." (PMID 35527812, 2022). "Indeed, plasma cytokine IL-1β, IL-10, and TNF-α levels are correlated with symptom intensity of pain, cramps, nausea, and vomiting, and associated with delayed gastric emptying, in H. pylori negative functional dyspepsia patients." (PMID 35527812, 2022). "Furthermore, duodenal transcript expression of IL-1β, but not TNF-α is increased in functional dyspepsia." (PMID 35527812, 2022).
Gingival bleeding (5 papers, 2018 to 2021). Hemorrhage affecting the gingiva. "In subjects with gingival bleeding of 30% or more, the mean IL-1β level was 265.31 pg/mL, which was higher than 81.80 pg/mL in the subjects with less gingival bleeding." (PMID 34199256, 2021). "Compared to the low gingival bleeding group, the levels of IL-1β in the high gingival bleeding group were significantly higher, and the levels of TNF-α were significantly lower in the high gingival bleeding group." (PMID 34199256, 2021).
Gliosis (5 papers, 2012 to 2022). Gliosis is the focal proliferation of glial cells in the central nervous system. "Gliosis plays an important role in the release of pro-inflammatory cytokines, such as IL-1β and tumor necrosis factor (TNF)-α and is a prominent feature of neurodegenerative conditions." (PMID 33430188, 2021). "Gliosis following Aβ plaque stimulation releases a variety of pro-inflammatory cytokines, including IL-1β, IL-6, and TNF-α, resulting in a persistent inflammatory response." (PMID 34439569, 2021). "Since mIns, as tCr, is considered a marker of glia cells, it is worth pointing out that no firm association between one-year change in mIns concentrations to levels of IL-1β and CXCL8 was observed, which one could argue should be demonstrated if both tCr and mIns represented gliosis." (PMID 23028598, 2012).